MFAP2 (microfibril associated protein 2)
Diseases named in the same sentence as MFAP2 in open-access papers (continued):
Sharing a sentence is not in itself a finding about the gene and the disease.
glioma (4 papers, 2022 to 2024). A benign or malignant brain and spinal cord tumor that arises from glial cells (astrocytes, oligodendrocytes, ependymal cells). "In the current study, by analyzing clinicopathological data from patients with glioma, we confirmed for the first time that MFAP2 is associated with the malignant phenotype of glioma, tumor-related pathways, and tumor immunity." (PMID 36204318, 2022). "The association between MFAP2 and immune cells suggests that MFAP2 plays a pivotal role in the regulation of tumor immunity in gliomas." (PMID 36204318, 2022). "Given the influence of 1p19q co-deletion and IDH status on glioma, we researched the association between these factors and MFAP2 expression." (PMID 36204318, 2022). "Furthermore, this study demonstrated that MFAP2 was strongly associated with the degree of immune infiltration in glioma, especially Th2 cells and macrophages." (PMID 36204318, 2022). "It affords crucial insight into the roles of MFAP2 in glioma and provides new directions for exploring the occurrence and development mechanism of glioma." (PMID 36204318, 2022). "Our findings underscore the key role of MFAP2 in glioma development and highlight its potential as a prognostic biomarker." (PMID 36204318, 2022). "Collectively, these findings highlight the potential of MFAP2 as a novel prognostic biomarker and a potential target for glioma immunotherapy." (PMID 36204318, 2022). "Subsequently, we observed that MFAP2 overexpression was related to the histological type of gliomas and was significantly overexpressed in glioblastoma multiforme." (PMID 36204318, 2022). "In conclusion, the current study verified the role of MFAP2 in malignant progression and immune microenvironment of glioma." (PMID 36204318, 2022). "The relationship between high MFAP2 expression and immune cell infiltration in glioma was further confirmed by an analysis of key immune cell markers." (PMID 36204318, 2022). "It was found that the expression of MFAP2 protein in glioma tissues was higher than that in the para-cancer tissues." (PMID 36204318, 2022). "We further verified disease special survival and progression-free interval and observed that both disease special survival and progression-free interval were lower in patients with glioma with high MFAP2 expression than in those with low MFAP2 expression." (PMID 36204318, 2022). "Since WHO grade, primary therapy outcome, age, IDH status, and 1p/19q codeletion are important clinicopathologic characteristics for glioma progression, we further performed ROC analysis combining MFAP2 expression with these parameters." (PMID 36204318, 2022). "We compared MFAP2 expression levels of gliomas of different grades in TCGA database and observed that MFAP2 positively correlated with glioma grade." (PMID 36204318, 2022). "MFAP2 expression was also correlated with chemokine receptors in gliomas, such as CCR3, CCR7, CXCR4, and CXCR6, which were significantly associated with MFAP2 expression in both LGG and GBM." (PMID 36204318, 2022). "Common clinicopathological parameters combined with the analysis of MFAP2 expression improve the predictive ability of OS in glioma patients." (PMID 36204318, 2022). "We further researched the relationship between MFAP2 expression and chemokines, chemokine receptors, and immunoinhibitors in gliomas." (PMID 36204318, 2022). "MFAP2 overexpression is relevant to poor prognosis and is considered an independent factor in patients with glioma." (PMID 36204318, 2022). "Contrastive research of 1,157 cases of normal tissues and 689 cases of glioma tissues in the TCGA-GTEx database showed that MFAP2 expression levels were significantly higher in glioma than in normal tissues (p < 0.001)." (PMID 36204318, 2022). "In this study, we investigated the influence of MFAP2 in patient survival and the correlation between MFAP2 expression and clinicopathological elements of glioma." (PMID 36204318, 2022).
glioma (continued). "High MFAP2 expression levels were markedly related to poorer overall survival of patients with glioma." (PMID 36204318, 2022). "GSEA was used for enrichment analysis of overexpressed MFAP2 to identify activated signaling pathways in gliomas." (PMID 36204318, 2022). "In our previous research, the expression level of MFAP2 in glioma was positively correlated with Th2 cells, macrophages, eosinophils, neutrophils and T cells." (PMID 36530974, 2022). "In addition, MFAP2 is a prognostic marker that correlates with the immune microenvironment in glioma." (PMID 36530974, 2022). "Based on the current literature, we hypothesized that MFAP2 plays an important role in malignant phenotype of glioma invasion, metastasis, and immunosuppression by remodeling tumor-related ECM components." (PMID 36204318, 2022). "The results of the functional analysis of MFAP2 protein in glioma revealed that MFAP2 correlated with signaling pathways activated in gliomas, such as activation of matrix metalloproteinases, MET promotion of cell motility, chemokine receptor binding to chemokines and cell cycle checkpoints." (PMID 36204318, 2022). "Multivariate analysis revealed that high MFAP2 expression was associated with low survival in patients with WHO G3/G4 glioma, IDH-mutated glioma and non-codeletion glioma." (PMID 36204318, 2022). "Our analyses revealed a correlation between MFAP2 and immune cell infiltration in gliomas." (PMID 36204318, 2022). "Furthermore, MFAP2 overexpression exhibited a strong ability to differentiate glioma from normal tissue, with an AUC value of 0.876." (PMID 36204318, 2022). "Additionally, MFAP2 expression level in glioma was positively correlated with key markers of T-cell exhaustion." (PMID 36530974, 2022). "However, the expression and effection of MFAP2 on gliomas have yet to be reported." (PMID 36204318, 2022). "Furthermore, we investigated the prognostic value of MFAP2 in glioma using a nomogram model." (PMID 36204318, 2022). "Our findings reveal that MFAP2 may be a valuable prognostic marker for gliomas." (PMID 36204318, 2022). "MFAP2 is highly expressed in a wide range of malignant tumors including GBM and plays a key role in glioma cell migration, proliferation, angiogenesis and was related to malignant phenotypes and to a poor prognosis of patients with GBM." (PMID 38272115, 2024). "In this study, Kaplan-Meier survival and Cox regression analysis showed that high MFAP2 expression levels predicted poor OS, DSS, and PFS in patients with glioma." (PMID 36204318, 2022). "In the present study, we systematically explored the transcriptome data related to glioma in TCGA and CGGA databases and observed that MFAP2 expression was meaningfully increased in glioma." (PMID 36204318, 2022). "Our research investigated MFAP2 expression is positively correlated to macrophages in TNBC and previous study has reported the overexpression of MFAP2 is positively related to markers of Th2 cells and M2 macrophages in glioma, implying MFAP2 performs a crucial role in tumor immunity modulation." (PMID 38822944, 2024).
Insulin resistance (4 papers, 2014 to 2025). Increased resistance towards insulin, that is, diminished effectiveness of insulin in reducing blood glucose levels. "In mice, Mfap2 deficiency is a well-known model of metabolic disease with consistent effects on increased adiposity, insulin resistance, hyperglycemia, and predisposition to diabetes." (PMID 39844333, 2025). "MAGP1-deficient (Mfap2−/−) mice display a progressive excess adiposity phenotype, which precedes insulin resistance and occurs without changes in caloric intake or ambulation." (PMID 27445989, 2016).
papillary thyroid cancer (4 papers, 2022 to 2025). "Upregulated MFAP2 expression in papillary thyroid cancer is associated with an increased recurrence or death risk." (PMID 36530974, 2022). "Studies have shown that MFAP2 expression can distinguish papillary thyroid cancer tissues from normal ones." (PMID 36530974, 2022). "In thyroid papillary carcinoma, MFAP2 downregulation inhibits BCPAP and TPC-1 cell migration and invasion; MFAP2 is associated with lymph node metastasis." (PMID 36530974, 2022). "A papillary thyroid carcinoma study showed that MFAP2 downregulation inhibited papillary thyroid carcinoma cell proliferation." (PMID 36530974, 2022). "MFAP2 increases the proliferation, motility and decreases the apoptosis of papillary thyroid cancer cells, and might be a potential therapeutic target for papillary thyroid cancer." (PMID 36530974, 2022). "Therefore, MFAP2 overexpression predicts a poor prognosis in papillary thyroid cancer." (PMID 36530974, 2022). "Therefore, MFAP2 downregulation promotes apoptosis in thyroid papillary carcinoma cells." (PMID 36530974, 2022). "In papillary thyroid carcinoma, whole-transcriptome sequencing was performed on tumor tissues and corresponding normal tissues adjacent to the carcinoma; the sequencing data were verified using RT-qPCR, confirming that MFAP2 was highly expressed in the tumor tissue." (PMID 36530974, 2022). "The downregulation of MFAP2 could inhibit BCPAP and TPC-1 cell migration and invasion and lymph node metastasis in thyroid papillary carcinoma." (PMID 40552117, 2025).
endometrial cancer (3 papers, 2019 to 2024). Primary or metastatic malignant neoplasm involving the endometrium (mucous membrane that lines the endometrial cavity). "In summary, our study integrates a complex proteomic landscape into actionable insights for endometrial cancer using the SHAP method for model interpretation—a novel approach that reveals the complex impact of individual proteins such as EWSR1 and MFAP2 on disease subtyping." (PMID 38894711, 2024).
esophageal cancer (3 papers, 2019 to 2025). A primary or metastatic malignant neoplasm involving the esophagus. "Considering that more than 90% of esophageal cancer patients were diagnosed as ESCC in China, to investigate the expression of MFAP2 in ESCC, we analyzed differentially expressed genes in EAC and ESCC tissues using TCGA-ESCA data." (PMID 40657371, 2025).
lymph node metastasis (3 papers, 2019 to 2024). "High expression of MFAP2 in CRC tissues was significantly associated with lymph node metastasis (N0, 52/95 vs. N1/2/3, 58/79; p = 0.011), distant metastasis (M0, 87/145 vs. M1, 23/29; p = 0.049), and advanced AJCC stage (stage 1/2, 49/92 vs. stage 3/4, 61/82, p = 0.004)." (PMID 36583532, 2023). "Microfibrillar-associated protein 2(MFAP2), which is closely associated with lymph node metastasis, distant metastasis, and the advanced AJCC stage in CRC, exhibits high expression levels in patients with CRC, influenced by m1A regulation." (PMID 38291517, 2024). "High expression of MFAP2 was closely related to lymph node metastasis and distant metastasis, leading to poor prognosis in patients with CRC." (PMID 36583532, 2023).
Osteopenia (3 papers, 2022 to 2024). Osteopenia is a term to define bone density that is not normal but also not as low as osteoporosis. "Mutations of MFAP2 gene may indicate thrombosis, thoracic aneurysms, metabolic diseases, and osteopenia in humans." (PMID 35211173, 2022). "In addition, MFAP2 is a bone remodeling regulator; its deficient mice show progressive osteopenia, accompanied by increased osteoclasts and NF- κB ligand-receptor activator expression." (PMID 36530974, 2022).
Breast invasive carcinoma (2 papers, 2011 to 2022). "MFAP2 expression in Bladder Urothelial Carcinoma, Breast invasive carcinoma, and Head and neck squamous cell carcinoma was detected using quantitative polymerase chain reaction (qPCR)." (PMID 36530974, 2022). "Stromal reaction to invasive breast carcinoma was associated with increased expression of genes encoding ECM components, proteolytic enzymes and adhesion receptors, including COL11A1, COL10A1, COMP, MMP11, FN1 and MFAP2, consistent with the abundant stromal remodeling observed by histology." (PMID 21611158, 2011).
breast tumor (2 papers, 2011 to 2021). "COL10A1, COL1A1, and MFAP2 are constituents of the extracellular matrix remodeling, which is an important process in breast tumor invasion and tumor cell dissemination." (PMID 34149812, 2021).
cholangiocarcinoma (2 papers, 2019 to 2022). A carcinoma that arises from the intrahepatic biliary tree (intrahepatic cholangiocarcinoma) or from the junction, or adjacent to the junction, of the right and left hepatic ducts (hilar cholangiocarcinoma). "The results showed that cholangiocarcinoma patients with deep deletion as the only mutation type had the highest frequency of MFAP2 alterations, exceeding 5%." (PMID 35211173, 2022).
colon adenocarcinoma (2 papers, 2021 to 2022). "The impact of inflammation-related factors and adipocyte-conditioned media (ACM) on MFAP2 mRNA levels in colon adenocarcinoma HT-29 cells were further analysed." (PMID 34445187, 2021). "The results showed that MFAP2 inhibits tumor cell apoptosis in colon adenocarcinoma." (PMID 36530974, 2022). "In colon adenocarcinoma, silencing MFAP2 promoted SW480 and HCT116 cell apoptosis." (PMID 36530974, 2022).
gastric adenocarcinoma (2 papers, 2022). "And in gastric adenocarcinoma, high MFAP2 expression was significantly correlated with the first progression and post-progressive survival shortening; the overall and disease-free survivals were shorter in patients with increased MFAP2 expression." (PMID 36530974, 2022).
head and neck squamous cell carcinoma (2 papers, 2019 to 2022). A squamous cell carcinoma that arises from any of the following anatomic sites: lip and oral cavity, nasal cavity, paranasal sinuses, pharynx, larynx, and salivary glands. "As a potential biomarker for prognosis and targeted therapy, MFAP2 is highly expressed in head and neck squamous cell carcinoma." (PMID 36530974, 2022). "In head and neck squamous cell carcinoma, the MFAP2 marker is expressed at higher levels (at least 13 times or more) in tumors than in normal tissues, as verified using RT-qPCR." (PMID 36530974, 2022). "As a potential biomarker of head and neck squamous cell carcinoma tumorigenesis, MFAP2 is significantly overexpressed in SAGE tumor libraries." (PMID 36530974, 2022).
liver cancer (2 papers, 2020 to 2022). An epithelial or non-epithelial malignant neoplasm that arises from the liver. "An in vitro experiment showed that downregulation of MFAP2 inhibited the proliferation and migration levels of liver cancer cells." (PMID 35211173, 2022). "Intriguingly, MFAP2 was also found to be an unfavorable indicator in multiple other cancers such as liver cancer, pancreatic cancer, renal cancer, and cervical cancer in our unpublished data." (PMID 32054827, 2020). "Moreover, the transcription factors, DNA methyltransferases, and immune factors in liver cancer might interact with MFAP2 and accelerate tumor progression." (PMID 35211173, 2022).
liver fibrosis (2 papers, 2023 to 2025). "Adeno-associated virus vector (serotype 6)-mediated Mfap2 overexpression in HSCs conferred protection against liver fibrosis in both models." (PMID 40213670, 2025). "We found that Microfibril Associated Protein 2 (MFAP2) was elevated in carbon tetrachloride (CCl4)‐induced liver fibrosis and Transforming Growth Factor‐Beta 1 (TGF‐β1)‐activated HSCs." (PMID 37635348, 2023). "Mfap2 deficiency (Mfap2 -/-) or overexpression (ovMfap2) mice were subjected to carbon tetrachloride (CCl4) injection or bile duct ligation (BDL) to induce liver fibrosis." (PMID 40213670, 2025). "Microfibrillar-associated protein 2 (MFAP-2) is a crucial component of the extracellular matrix (ECM) microfibrils, yet its role in liver fibrosis remains elusive." (PMID 40213670, 2025). "In vitro results showed that the inhibition of MFAP2 alleviated hepatic fibrosis by inhibiting the activation and inducing the apoptosis of active HSCs in a CCl4‐induced mouse model." (PMID 37635348, 2023). "In conclusion, our results suggest that MFAP2 is a potential target for the clinical treatment of liver fibrosis." (PMID 37635348, 2023). "In conclusion, to the best of our knowledge, this is the first study to demonstrate the potential role of MFAP2 in the activation of HSCs during liver fibrosis." (PMID 37635348, 2023). "MFAP2 was significantly overexpressed in liver fibrosis and activated HSCs after continuous inflammatory stimulation." (PMID 37635348, 2023). "Additionally, we validated the role of Mfap2 deletion in liver fibrosis using the BDL mouse model, demonstrating a more pronounced effect on fibrosis progression." (PMID 40213670, 2025). "Our data suggested that MFAP2 might be involved in liver fibrosis by regulating the expression of FBN1." (PMID 37635348, 2023). "Then the role of MFAP2 in liver fibrosis both in vivo and in vitro." (PMID 37635348, 2023). "Our findings suggest that targeting MFAP2 may be a promising interventional strategy for liver fibrosis in the future." (PMID 37635348, 2023). "Enhancing MFAP-2 in HSCs may therefore benefit patients with liver fibrosis." (PMID 40213670, 2025). "Furthermore, MFAP2 expression was significantly upregulated in LX‐2 cells with TGF‐β1 treatment both at mRNA and protein level, which suggested that abnormal MFAP2 expression might participate in the progression of liver fibrosis." (PMID 37635348, 2023). "Furthermore, overexpression of FBN1 remarkably restored the cell proliferation and inhibited cell apoptosis as compared to control, suggesting that MFAP2 mediated TGF‐β/Smad3 signalling pathway and fibrotic markers during liver fibrosis by upregulating the expression of FBN1." (PMID 37635348, 2023). "However, no studies have reported the function of MFAP2 in liver fibrosis." (PMID 37635348, 2023).
osteosarcoma (2 papers, 2020 to 2023). A usually aggressive malignant bone-forming mesenchymal neoplasm, predominantly affecting adolescents and young adults. "The intracellular form of MFAP2 can induce the transcription of integrin α4 in human osteosarcoma cell line SAOS-2 in vascular development." (PMID 36936373, 2023).
prostate carcinoma (2 papers, 2011 to 2021). A carcinoma that arises from epithelial cells of the prostate gland. "In this sense, opposite gene expression levels of MFAP2 have been described in different tumour types as being upregulated in gastric, thyroid and hepatocellular carcinomas and downregulated in prostate carcinoma and paragangliomas." (PMID 34445187, 2021).
chondrosarcoma (1 paper, 2022). A malignant cartilaginous matrix-producing mesenchymal neoplasm arising from the bone and soft tissue. "MFAP2 is a poor prognosis marker in chondrosarcoma malignant transformation; its high expression predicts poor prognosis." (PMID 36530974, 2022).
chronic obstructive pulmonary disease (1 paper, 2023). A chronic and progressive lung disorder characterized by the loss of elasticity of the bronchial tree and the air sacs, destruction of the air sacs wall, thickening of the bronchial wall, and mucous accumulation in the bronchial tree. "MFAP2 is a glycoprotein which is a component of elastin-associated microfibrils, with SNPs in this gene associated with chronic obstructive pulmonary disease and lung function." (PMID 36725857, 2023).
colorectal adenocarcinoma (1 paper, 2022). The most common type of colorectal carcinoma. "In colorectal adenocarcinoma, the MFAP2 mRNA expression in tumor tissues was significantly higher than that in the adjacent non-tumor tissues." (PMID 36530974, 2022). "In vitro colorectal adenocarcinoma studies found that MFAP2 silencing inhibited the migration of SW480 and HCT116 cells." (PMID 36530974, 2022). "MFAP2 may be involved in the development of Colorectal adenocarcinoma." (PMID 36530974, 2022).
ductal adenocarcinoma (1 paper, 2022). "In addition, we conducted in vitro investigations that demonstrated that knuckling of MFAP2 suppressed the proliferation and migration of ductal adenocarcinoma cells, which might constitute a biomarker for STAD, to examine whether or not MFAP2 silencing is contributing to the suppression of tumors." (PMID 35356627, 2022).